PATE1 (prostate and testis expressed 1)
Synonyms: PATE
Tractability: Antibody: UniProt places it where antibodies can reach, with high confidence; UniProt predicts a signal peptide or a membrane-spanning region; its Gene Ontology location is reachable by antibodies, with medium confidence.
Gene: Protein-coding gene on chromosome 11 (125,746,279 to 125,749,867, forward strand). Ensembl gene ENSG00000171053.
Subcellular location: Secreted
Gene Ontology:
Molecular function: protein binding; acetylcholine receptor regulator activity
Cellular component: extracellular region
Genetic constraint (gnomAD): Loss-of-function variants: 22 observed, 14.72 expected, observed/expected ratio (o/e) 1.49, 90% interval 1.05 to 1.91. The upper end of that interval is the gene's LOEUF score, 1.91, which puts it in group 6 of 6, group 1 being the genes least tolerant of losing a copy. Missense variants: 166 observed, 154.85 expected, observed/expected ratio (o/e) 1.07, 90% interval 0.94 to 1.22. Synonymous variants: 52 observed, 50.08 expected, observed/expected ratio (o/e) 1.04, 90% interval 0.83 to 1.31.
Homologues: Orthologues: chimpanzee PATE1 (99% identical), macaque PATE1 (82% identical), guinea pig PATE1 (63% identical), rat Pate1 (63% identical), rabbit PATE1 (62% identical), mouse Pate1 (61% identical), dog PATE1 (55% identical), pig PATE1 (54% identical). Paralogues in human: PATE3 (29% identical), ACRV1 (25% identical), PATE4 (19% identical), PATE2 (14% identical).
Diseases named in the same sentence as PATE1 in open-access papers:
PATE1 is named in the same sentence as 4 diseases in open-access papers, as found by Europe PMC text mining. Sharing a sentence is not in itself a finding about the gene and the disease. The quoted sentences say what the papers report.
asthenozoospermia (4 papers, 2019 to 2023). "The analysis of polymorphisms in PATE1 gene suggested that its variant is a high risk genetic factor for human idiopathic asthenozoospermia." (PMID 34440724, 2021). "Further, previous studies showed asthenozoospermia patients having reduced levels of PATE1, and that single nucleotide polymorphisms were found in idiopathic asthenozoospermia." (PMID 30927342, 2019). "In the context of differentially expressed (DE)-genes related to asthenozoospermia, special attention has recently been focused on Cysteine-Rich Secretory Protein 2 (CRISP2), Cation Channel Sperm Associated 1 (CATSPER1) and Prostate and Testis Expressed 1 (PATE1)." (PMID 34440724, 2021). "The purpose of this study was to analyze the expression level of CRISP2, CATSPER1, PATE1 and SEMG1 genes in the sperm of men with asthenozoospermia (AZS)." (PMID 31058050, 2019).
cancer (1 paper, 2019). A tumor composed of atypical neoplastic, often pleomorphic cells that invade other tissues. "Moreover, PATE1 is also found to have a very low standarddeviation of gene expression within all cancer types." (PMID 31831960, 2019).
PATE1 also shares sentences with these, for which no sentence is quoted: bacterial infection (1 paper); infection (1).